KLF8 (KLF transcription factor 8)
Diseases named in the same sentence as KLF8 in open-access papers (continued):
Sharing a sentence is not in itself a finding about the gene and the disease.
gastric cancer (14 papers, 2013 to 2025). A primary or metastatic malignant neoplasm involving the stomach. "Furthermore, we found that KLF8 expression was significantly associated with larger tumour size and advanced TN stage for gastric cancer after gastrectomy in both TCGA and our database." (PMID 31124603, 2019). "Further investigations revealed that KLF8 increases the expression of P-gp and Bcl-2 and decreases the expression of Bax and Caspase-3 in gastric cancer cells." (PMID 36846589, 2023). "Mao et al44 also illustrated the poor survival impact of KLF8 in gastric cancer, which regulated glycolysis by affecting GLUT4." (PMID 32281273, 2020). "In conclusion, here we demonstrate that KLF8 is a novel prognostic biomarker for survival in gastric cancer, and silencing KLF8 expression impairs glycolysis by targeting GLUT4 in gastric cancer cells." (PMID 31124603, 2019). "High KLF8 expression was significantly correlated with worse DFS for patients with gastric cancer after gastrectomy (χ2 = 17.58, P < 0.001)." (PMID 31124603, 2019). "Here, we examined KLF gene expression in five paired liver metastases and primary gastric cancer tissues by RT‐PCR, and immunohistochemistry was used to study KLF8 expression in 206 gastric cancer samples." (PMID 31124603, 2019). "In a series of 32 gastric cancer patients, we found higher SUVmax value in patients with high KLF8 expression than those with low expression." (PMID 31124603, 2019). "As the TCGA database lacks therapy information, we then validated the significance of KLF8 by IHC in gastric cancer using our own database of 206 gastric cancer samples." (PMID 31124603, 2019). "In human breast and gastric cancer, overexpression of KLF8 has been shown to predict poor prognosis." (PMID 24429391, 2014). "KLF8 plays an important role in oncogenic transformation in several types of human cancer such as breast cancer, gastric cancer." (PMID 23722127, 2013). "Since the lack of VHL, which results in the stabilization of HIF-1α, is related to the overexpression of KLF8 in renal cell carcinoma, the research group investigated whether KLF8 is involved in hypoxia-induced chemoresistance in gastric cancer." (PMID 36846589, 2023). "High nuclear KLF8 expression is observed in the diffuse type of gastric cancer." (PMID 35743973, 2022). "KLF8 was recently shown to be upregulated in many gastric cancer patient samples, which correlated with a higher maximum standardized uptake value (SUVmax), increased glucose utilization, lactate concentrations, and ATP production indicating the Warburg effect." (PMID 36077352, 2022). "Moreover, by targeting GLUT4, the silence of krüppel-like transcription factor 8 (KLF8) expression decreased the glycolysis rate of gastric cancer cells in vitro." (PMID 34488531, 2021). "We investigated KLF8 expression and function in gastric cancer and its clinical significance." (PMID 31124603, 2019). "Silencing KLF8 expression impaired the glycolysis rate of gastric cancer cells in vitro." (PMID 31124603, 2019). "Our results show that KLF8 can promote glycolysis in gastric cancer by targeting GLUT4." (PMID 31124603, 2019). "Furthermore, our functional study of GLUT4 indicated that its expression correlated with poor survival of gastric cancer and glycolysis rate in gastric cancer cells, which is consistent with the survival and functional study of KLF8 in gastric cancer." (PMID 31124603, 2019). "KLF8 overexpression is correlated with angiogenesis and poor prognosis in gastric cancer." (PMID 31624471, 2019). "In the present study, we first systematically examined the gene expressions of KLF family members in liver metastases and corresponding gastric cancer tissues and found that KLF8 was most significantly up‐regulated in liver metastases among all KLF family members." (PMID 31124603, 2019). "We thus next investigated whether KLF8 may play a function in glycolysis in gastric cancer." (PMID 31124603, 2019).
gastric cancer (continued). "In addition, KLF8 is necessary for gastric cancer cell survival and invasion." (PMID 23722127, 2013). "They observed that the expression of KLF8 increased substantially under hypoxic conditions in parallel to HIF-1α in MKN45, MKN28, and SGC7901 gastric cancer cells." (PMID 36846589, 2023). "Also, Krüppel-like factor 8 (KLF8) enhances EMT induction through direct suppression of E-cadherin by regulating its promoter, resulting in improved motility and altered cell morphology, which has been implicated in breast, ovarian, and gastric cancer cell lines." (PMID 34868979, 2021). "For instance, Krüppel-like factor 8 (KLF8) promotes EMT in breast, ovarian and gastric cancer cell lines." (PMID 32318352, 2020). "Hence, KLF8 may be a new biomarker and potential therapeutic target for gastric cancer treatment." (PMID 31124603, 2019). "KLF8 expression was silenced in AGS and MGC803 gastric cancer cells by lentivirus‐mediated method, and knockdown efficiency was confirmed by RT‐PCR and Western blotting." (PMID 31124603, 2019). "KLF8, a potent EMT-regulator, is induced by TGFß1 and acts as an indispensable player in the TGFß-mediated EMT in gastric cancer cells." (PMID 24429391, 2014). "In agreement with our finding, several studies demonstrated that knocking down KLF8 in the U87-MG glioma cells, 786-0 renal cells, and SGC-7091 gastric cancer cells, HCC hepatocellular carcinoma dramatically inhibited the cells proliferation." (PMID 23722127, 2013). "KLF8 activates invasion in cooperation with focal adhesion kinase (FAK) by increased transcription of matrix metalloproteinase-14 (MMP14, also known as MT1-MMP) in gastric cancer cells." (PMID 24429391, 2014). "Importantly, KLF8 and GLUT4 showed consistent expression patterns in gastric cancer tissues." (PMID 31124603, 2019). "Importantly, KLF8 and GLUT4 showed similar expression patterns in gastric cancer tissues." (PMID 31124603, 2019).
ovarian carcinoma (12 papers, 2013 to 2024). A malignant neoplasm originating from the surface ovarian epithelium. "These authors also found that upon KLF8 overexpression, ovarian cancer cells display increased BCL2 expression that promotes cell survival." (PMID 38256218, 2024). "KLF8 is widely expressed in various tissues, and abnormal expression of KLF8 is manifested in several cancers, including lung, gastric and ovarian cancers." (PMID 37864310, 2023). "We have demonstrated that both PI-3 kinase and Src play a role in FAK-induced upregulation of KLF8 in fibroblasts and ovarian cancer cells and in the latter activation of SP1 downstream of Akt plays a likely role." (PMID 26993780, 2016). "Sp1 has been suggested to be responsible for many features of ovarian cancer cells like oncogenic transformation and epithelial to mesenchymal transition for example through activation of KLF8." (PMID 25265318, 2014). "Sp-1 also serves as a docking site for binding with CD11b which causes transcriptional activity and is also essential for FAK activation of Krüppel- like factor 8 (KLF8) promoter in human ovarian cancer cells." (PMID 23970932, 2013). "KLF8 transcription is activated by FAK in human ovarian cancer cells." (PMID 31624471, 2019). "Three affected genes, HUWE1, PHF8 and KLF8, are related to breast or ovary cancers." (PMID 29558483, 2018). "For instance, KLF8 is activated by transforming growth factor-β1 (TGF-β1) via SMAD2 and contributes to ovarian cancer progression." (PMID 38256218, 2024). "TGF-β/SMAD2/KLF8 axis regulates epithelial–mesenchymal transition (EMT) and contributes to ovarian cancer progression." (PMID 39057685, 2024). "For example, KLF8 has been reported to transduce FAK to PI3K to AKT to SP1 signaling to up regulate cyclin D1 expression and enhance the cell cycle progression in ovarian cancer cell." (PMID 23722127, 2013). "To further investigate the mechanism by which C17orf91 elicited its oncogenic role, we explored whether C17orf91 could regulate key pro-metastatic genes, such as KLF8, MYC, SNAI2, TWIST1, ZEB1 and ZEB2 in ovarian cancer." (PMID 27535740, 2016).
hepatocellular carcinoma (10 papers, 2012 to 2025). A malignant tumor that arises from hepatocytes. "In lung cancer and hepatocellular carcinoma, overexpression of KLF8 was associated with decreased patient survival." (PMID 35345512, 2022). "In human hepatocellular carcinoma, up-regulation of KLF8 promotes tumor invasion and indicates poor prognosis." (PMID 31624471, 2019). "Furthermore, KLF8 overexpression was demonstrated in highly metastatic or recurrent hepatocellular carcinomas (HCC)." (PMID 22276196, 2012). "Similar conclusions resulted from a study in hepatocellular carcinoma, attributing a pro-invasive role to KLF8, conferring early relapse in human HCC." (PMID 24429391, 2014). "Here we report the mechanisms by which KLF8 crosstalks with Wnt/β-catenin signaling pathway and regulates hepatocellular carcinoma (HCC) cells proliferation." (PMID 22761862, 2012). "However, the functional role of KLF8 in the pathogenesis of hepatocellular carcinoma (HCC) remains largely unknown." (PMID 32874135, 2020). "Even if KLF8 has been depicted an ubiquitous factor, this is surprising since other highly proliferative non-CNS tumors such as recurrent hepatocellular carcinomas or renal cell carcinomas demonstrated significant overexpression of this signaling molecule." (PMID 22276196, 2012).
glioma (6 papers, 2012 to 2020). A benign or malignant brain and spinal cord tumor that arises from glial cells (astrocytes, oligodendrocytes, ependymal cells). "Inhibition of this potent transcription factor led to an almost complete loss of glioma cell proliferation in vitro, but its ubiquitous expression might counteract KLF8-targeting in malignant gliomas as a future antiproliferative strategy." (PMID 22276196, 2012). "KLF8-knockdown by shRNA in U87 glioma cells has been reported to suppressed tumor cell proliferation." (PMID 23722127, 2013). "Nevertheless, this work significantly advances our knowledge on glioma specific KLF8 expression patterns but independent functional relevance." (PMID 22276196, 2012). "While KLF8 was expressed in almost all glial tumors, only a limited fraction of the tumor cells were found to be immunopositive for the Ki67." (PMID 22276196, 2012). "Immunohistochemical staining for KLF8 demonstrated abundant protein expression in glial tumors of different WHO grades." (PMID 22276196, 2012). "Our immunohistochemical and Western blot studies demonstrate for the first time that KLF8, a pivotal transcription factor for cell cycle proliferation, is expressed in gliomas of different WHO grades." (PMID 22276196, 2012). "Since KLF8 has been demonstrated to be essential in proliferation of non-glial tumors, we selectively inhibited KLF8 by shRNA transfection in U87-MG glioma cell line (detected positive for KLF8)." (PMID 22276196, 2012). "In the present study, we show for the first time the expression of KLF8 in gliomas of different WHO grades and its functional impact on glioma cell proliferation." (PMID 22276196, 2012). "In glioma cells, KLF8 also promotes temozolomide resistance by activating β-catenin." (PMID 31624471, 2019). "KLF8 is barely expressed in normal human epithelial cells but highly overexpressed in several types of cancer cell lines established from human patients, including ovarian, gliomas, breast, gastric and renal carcinomas." (PMID 23722127, 2013). "It now has to be elucidated whether KLF8 regulation follows similar mechanisms in glioma models in order to identify possible new key molecules." (PMID 22276196, 2012). "Hence, we subjected U87-MG cells to shRNA-knockdown of KLF8, which led to a significant time dependent impairment in their proliferation, providing first evidence for the potency of this transcription factor in human gliomas." (PMID 22276196, 2012). "Even if KLF8 is a putative proliferation marker in other non-glial tumor entities, not all KLF8 immunopositive glioma cells did also stain positive for Ki67, which is a widely used proliferation marker in glial tumors." (PMID 22276196, 2012). "Although this might implicate similarities in glial tumors, detailed knowledge about morphological KLF8 expression in gliomas is still lacking." (PMID 22276196, 2012). "In order to get information about KLF8-mRNA regulation qPCR was performed and did not reveal any significant difference in samples (n = 10 each) of non-neoplastic brain (NNB), low-grade gliomas (LGG, WHO°II) and glioblastomas (GBM, WHO°IV)." (PMID 22276196, 2012).
osteosarcoma (6 papers, 2014 to 2025). A usually aggressive malignant bone-forming mesenchymal neoplasm, predominantly affecting adolescents and young adults. "KLF8 has a negatively associated expression level with miR-429 in osteosarcoma, and an elevated KLF8/miR-429 ratio suggests a high tumorigenic potential." (PMID 36761967, 2023). "Besides, we also found that the function of circSAMD4A in osteosarcoma was partially exerted via the miR-218-5p/KLF8 axis, which provided new insight into the mechanisms underlying the chemoresistance of osteosarcoma and potential therapeutic targets for osteosarcoma chemotherapy." (PMID 33817271, 2020). "For instance, a decrease in KLF8 expression slows down the proliferation of differentiated cells (cancerous osteoblasts) or metastases in osteosarcomas, and FHL2 positively affects osteoblastogenesis, bone formation, and bone mass." (PMID 35455019, 2022). "In all, circSAMD4A enhanced cell DXR resistance in osteosarcoma by regulating the miR-218-5p/KLF8 axis, suggesting a novel therapeutic target for therapy-resistant osteosarcoma." (PMID 33817271, 2020). "In this study, we uncovered that KLF8 was elevated in DXR-resistant cell lines and tissues, and KLF8 knockdown promoted the cytotoxicity of DXR in osteosarcoma." (PMID 33817271, 2020). "Thus, we hypothesized that KLF8 might be associated with osteosarcoma chemoresistance." (PMID 33817271, 2020). "CircSAMD4A and KLF8 were elevated in osteosarcoma, and knockdown of circSAMD4A or KLF8 sensitized osteosarcoma cells to DXR by mediating resistant cell viability, migration and invasion inhibition, and cell cycle arrest in vitro." (PMID 33817271, 2020). "Although overexpression of KLF8 has been observed in a variety of human tumor types, the role of KLF8 in human osteosarcoma is yet to be elucidated." (PMID 24604387, 2014). "In the present study, lentivirus-mediated siRNA was employed to knockdown KLF8 expression in the Saos-2 human osteosarcoma cell line." (PMID 24604387, 2014). "Knockdown of KLF8 was found to significantly inhibit proliferation and invasion in osteosarcoma cells." (PMID 24604387, 2014). "The present study identified the important role of KLF8 in osteosarcoma and its potential as a biomarker for diagnosis and therapy." (PMID 24604387, 2014). "Therefore, we demonstrated that circSAMD4A positively regulated KLF8 via miR-218-5p in osteosarcoma cells." (PMID 33817271, 2020). "Recently, KLF8 was found to promote osteosarcoma carcinogenesis and progression." (PMID 33817271, 2020). "In addition, we also revealed that circSAMD4A positively regulated KLF8 through acting as a sponge of miR-218-5p, and thus, a circSAMD4A/miR-218-5p/KLF8 network in osteosarcoma cells was identified." (PMID 33817271, 2020). "Given that KLF8 was positively correlated with circSAMD4A in osteosarcoma, we wanted to know whether circSAMD4A regulated KLF8 via miR-218-5p." (PMID 33817271, 2020). "Thus, we concluded that circSAMD4A knockdown promoted DXR-induced tumor suppression in osteosarcoma murine xenograft models by regulating miR-218-5p and KLF8 expression." (PMID 33817271, 2020). "Importantly, this study first verified that miR-218-5p directly targeted KLF8, and miR-218-5p regulated DXR resistance via KLF8 in osteosarcoma." (PMID 33817271, 2020). "Additionally, circSAMD4A knockdown enhanced the cytotoxicity of DXR in osteosarcoma in vivo via regulating miR-218-5p and KLF8." (PMID 33817271, 2020). "We then studied whether the action of miR-218-5p in DXR resistance in osteosarcoma cells was mediated by KLF8." (PMID 33817271, 2020). "In this study, we attempted to detect the functions of circSAMD4A, miR-218-5p and KLF8 in DXR resistance in osteosarcoma and explored whether there was a potential regulatory network among circSAMD4A, miR-218-5p and KLF8." (PMID 33817271, 2020). "The effects of KLF8 on osteosarcoma cell growth and invasion were subsequently investigated." (PMID 24604387, 2014).
osteosarcoma (continued). "The present study aimed to investigate the biological impact of KLF8 on Saos-2 osteosarcoma cells." (PMID 24604387, 2014). "The present study provides evidence that lentivirus-mediated KLF8 knockdown inhibits growth and invasion in osteosarcoma cells, suggesting that KLF8 may be a potential therapeutic biomarker for osteosarcoma." (PMID 24604387, 2014). "The invasive potential of Saos-2 cells was significantly reduced with lentivirus-mediated KLF8 siRNA treatment compared with the control group (P<0.05), indicating that KLF8 may have a role in promoting osteosarcoma cell invasion." (PMID 24604387, 2014). "Thus, KLF8 knockdown suppressed DXR resistance in osteosarcoma cells." (PMID 33817271, 2020). "Besides, miR-218-5p was found to bind to circSAMD4A or KLF8, and subsequent rescue experiments indicated that miR-218-5p inhibition reversed the inhibitory effects of circSAMD4A silencing on DXR resistance, and silencing miR-218-5p enhanced DXR resistance by targeting KLF8 in osteosarcoma cells." (PMID 33817271, 2020). "The levels of circSAMD4A, miR-218-5p and KLF8 were detected, and the results showed that relative to the non-tumor tissues and normal cell line hFOB, circSAMD4A and KLF8 were elevated, while miR-218-5p was decreased in osteosarcoma tissues and cell lines (HOS and U2OS)." (PMID 33817271, 2020). "Additionally, we also discovered that miR-218-5p expression was negatively correlated with circSAMD4A (r = −0.7051, P < 0.0001) and KLF8 (r = −0.8618, P < 0.0001), and KLF8 expression was positively correlated with circSAMD4A in osteosarcoma tissues (r = 0.7564, P < 0.0001)." (PMID 33817271, 2020). "Therefore, lentivirus-mediated KLF8 siRNA treatment may be an effective therapeutic strategy for osteosarcoma." (PMID 24604387, 2014). "In conclusion, this study demonstrated that knockdown of circSAMD4A or KLF8 and elevation of miR-218-5p restored the DXR sensitivity of osteosarcoma cells." (PMID 33817271, 2020). "However, the function of KLF8 in human osteosarcoma remains unknown." (PMID 24604387, 2014). "KLF8 is a dual transcription factor and can either suppress or activate the transcription of target genes, including cyclin D1, KLF4 and E-cadherin, which are related to tumor development in diverse cancer types including osteosarcoma." (PMID 33817271, 2020). "Similarly, in contrast with the parental osteosarcoma cell lines HOS and U2OS, circSAMD4A and KLF8 were also significantly increased and miR-218-5p was decreased in DXR-resistant cell lines HOS/DXR and U2OS/DXR." (PMID 33817271, 2020).